CD80 (CD80 molecule)
Diseases named in the same sentence as CD80 in open-access papers (continued):
Sharing a sentence is not in itself a finding about the gene and the disease.
rectal cancer (2 papers, 2020 to 2021). A primary or metastatic malignant neoplasm that affects the rectum. "Expression of CD80 on DCs treated with TCM from irradiated rectal cancer tissue correlated with levels of ICAM-1 (r = 0.8214, p = 0.03) and CD11c correlated with IL-1RA (r = 0.7619, p = 0.03)." (PMID 33540635, 2021). "We demonstrated a significant increase in CD80 and PD-L1 on the DCs exposed to the irradiated rectal cancer secretome compared to the mock-irradiated rectal cancer secretome." (PMID 33540635, 2021). "Interestingly, however, the irradiated rectal cancer secretome induced the most potent effect on dendritic cell maturation via upregulation of CD80 and PD-L1." (PMID 33540635, 2021). "However, TCM from irradiated rectal cancer biopsies had the least inhibitory effect on CD80 levels, inducing significantly higher expression of CD80 compared to TCM from mock-irradiated rectal cancer (p = 0.03)." (PMID 33540635, 2021). "While in the rectal cancer TME, CD80 levels on DCs correlated positively with Flt-1 and inversely with IL-27." (PMID 33540635, 2021). "In the irradiated rectal cancer, TME CD80 correlated with ICAM-1 and CD11c correlated with IL-1RA." (PMID 33540635, 2021).
renal carcinoma (2 papers, 2022 to 2023). A carcinoma arising from the epithelium of the renal parenchyma or the renal pelvis. "Current major immunotherapies in cancer, including renal cancer, are based on the blocking by specific monoclonal antibodies of the binding of the B7 immune checkpoint proteins CD80/B7-1 and CD86/B7-2, and PD-L1/B7-H1 and PD-L2/B7-DC, with their co-receptors CTLA-4 and PD-1, respectively." (PMID 35563753, 2022).
Salmonella Infections (2 papers, 2008 to 2015). Infections with bacteria of the genus SALMONELLA. "Splenocyte dendritic cell CD80 expression is similar in both groups of un-infected mice but is significantly up-regulated with Salmonella infection only in the placebo group." (PMID 18670628, 2008). "The data thus far suggest that differences in DC subset abundance or CD80/86 expression on DCs, as well as CD4+ or CD8+ T cell numbers in infected tissues, do not explain the observed difference in survival of the mouse strains to Salmonella infection." (PMID 26441965, 2015). "Thus, the observed differences in survival of the mouse strains to oral Salmonella infection are independent of differential recruitment of myeloid cells, DC abundance, and expression of CD80 and CD86 on DCs in infected tissues." (PMID 26441965, 2015).
Sjögren’s syndrome (2 papers, 2021 to 2024). "Interestingly, splenic MDSCs of mice in early stage of experimental Sjögren’s syndrome (10 days postimmunization) showed an immature phenotype (low expression levels of CD40, CD80, CD86 and MHC-II markers) and potent suppressive activity of T cell proliferation." (PMID 38495880, 2024).
systemic scleroderma (2 papers, 2022). "Another study has reported circulatory macrophage (CD204+CD163+CD206+TLR4+CD80+CD86+) and monocyte (CD14+CD206+CD163+CD204+TLR4+CD80+CD86+) populations that expressed both M1/M2 markers in systemic sclerosis patients and in interstitial lung disease (ILD)." (PMID 35603185, 2022).
triple-negative breast carcinoma (2 papers, 2022). An invasive breast carcinoma which is negative for expression of estrogen receptor (ER), progesterone receptor (PR), and human epidermal growth factor receptor 2 (HER2). "Furthermore, we found CD80 showed higher expression in triple-negative breast cancer (TNBC) when compared with the non-TNBC group." (PMID 35814211, 2022).
ZIKV infection (2 papers, 2017 to 2024). "Our results showed that intermediate-activated monocytes, in response to ZIKV infection, exhibited adhesion (CD11b+ CD11c+) properties and expressed co-stimulatory molecules (CD80+ CD86+)." (PMID 38247836, 2024). "To determine the ability of ZIKV infection to program DCs, we measured cell surface expression of co-stimulatory (CD80, CD86, and CD40) and MHC class II molecules at 48hpi with all four ZIKV strains." (PMID 28152048, 2017). "Our findings suggest that, during ZIKV infection, human monocytes differentiate from the classical to the intermediate phenotype and that they enter an activated state that is maintained up to 96 h p.i., with detectable levels of CD11b, CD11c, CD80, CD86, and viral E/NS1 proteins." (PMID 38247836, 2024).
AA amyloidosis (1 paper, 2025). Secondary amyloidosis is a form of amyloidosis, that complicates chronic inflammatory disorders (mainly rheumatoid arthritis) and is characterized by the aggregation and deposition of amyloid fibrils composed of serum amyloid A protein, an acute phase reactant. "There is also limited evidence indicating the successful application of IL-12/23 agents, JAK agents, and CD80/CD86-CD28 costimulatory pathway agents in AA amyloidosis." (PMID 40901513, 2025).
abdominal abscess (1 paper, 2009). An abscess located in the abdominal cavity, i.e., the cavity between the diaphragm above and the pelvis below. "Interestingly, recent studies suggest CD86, not CD80, plays a dominant role in mediating graft vs. host disease and abdominal abscess formation." (PMID 19672303, 2009).
acute leukemia (1 paper, 2024). A clonal (malignant) hematopoietic disorder with an acute onset, affecting the bone marrow and the peripheral blood. "Similarly, in acute leukemias expressing myeloid and lymphoid-associated antigens, the presence of CD80+ tumor cells would support an AML." (PMID 39224452, 2024). "Given that a few dogs with AML only had positive results with single myeloid antigens, our results show that antibodies against multiple myeloid antigens should be applied when immunophenotyping an acute leukemia, including CD80." (PMID 39224452, 2024). "Since monocytic variants are the most common subtype of AML in dogs, we reasoned that if CD80 is expressed on normal canine monocytes, it may be a helpful flow cytometric marker to confirm AML in a dog with acute leukemia." (PMID 39224452, 2024).
acute pancreatitis (1 paper, 2018). An acute inflammatory process that leads to necrosis of the pancreatic parenchyma. "We observed decreases in lymphocytes, CD19+, B10, CD19+CD24hiCD27hi cells and lower mean fluorescence intensity (MFI) of CD80 and CD86 on B10 or CD19+CD24hiCD27hi cells in patients with AP, especially in those with severe acute pancreatitis (SAP)." (PMID 30546828, 2018).
allergic aspergillosis (1 paper, 2023). "Both CD86 and its paralog CD80 were upregulated in a model of experimental allergic aspergillosis, demonstrating a significant role for these co-stimulatory molecules in onset, persistence, and progression of immune responses." (PMID 37277347, 2023).
allergic rhinitis (1 paper, 2025). Inflammation of the nasal mucous membranes caused by an IgE-mediated response to external allergens. "Shikonin has been shown to alleviate excessive Th2 cell activation in rat models of allergic rhinitis by reducing the expression of co-stimulatory molecules CD80 and CD86 on dendritic cells while concurrently reducing the circulating levels of IL-4 in peripheral blood." (PMID 41560747, 2025).
anaphylaxis (1 paper, 2019). An acute hypersensitivity reaction that occurs from exposure to an allergen. "Moreover, the SAV also disturbs various immunological parameters including expression of PMNs, CD-80, CD-86, interleukins and other cytokines compromising the affected organism towards mild to severe allergic reactions including life-risking anaphylaxis." (PMID 31847893, 2019).
anaplastic thyroid carcinoma (1 paper, 2018). "Here, the expression of PD-L1, PD-L2, CD80, and CD86 was evaluated at the mRNA level in 94 patients affected by papillary thyroid carcinoma (PTC) and 11 patients affected by anaplastic thyroid carcinoma (ATC)." (PMID 30123257, 2018).
ANCA-associated vasculitis (1 paper, 2023). "Further, mechanistic studies in ANCA-associated vasculitis identified CD28null T cells acting independently of the CD28/CD80 pathway, which may explain why CD80/CD86 inhibition in ANCA disease may not be optimal." (PMID 36598752, 2023).
Anxiety (1 paper, 2024). Intense feelings of nervousness, tension, or panic often arise in response to interpersonal stresses. "Its daily application results in lower rates of disability and anxiety and lower levels of IL-8 and CD-80 on peripheral monocytes and TNF." (PMID 39337066, 2024).
arterial disease (1 paper, 2024). "For example, CD80/CD86 co-stimulation plays a role in promoting graft arterial disease after heart transplantation." (PMID 39926714, 2024). "Blocking CD80/CD86 at a later stage or selectively blocking CD80 alone can reduce the progression of graft arterial disease, but early graft loss was not prevented by CD80 blockade alone, unlike the more effective CD80/CD86 double blockade." (PMID 39926714, 2024).
arteritis (1 paper, 2025). An inflammatory process affecting an artery. "Specifically, CD4+ T cells are triggered by class-II major histocompatibility complex (MHC-II) and co-stimulatory molecules (CD80 and CD86), then infiltrated all the layers of the artery, leading to pan-arteritis." (PMID 39762453, 2025).
arthropathy (1 paper, 2021). Any disorder of the joints. "This study revealed that, in the IFP of arthropathy patients, abundant CD14-positive cell stores and the ratio of CD14++CD80+ cells/CD14++CD163+ cells were elevated, implying the localization of inflammation in the IFP." (PMID 34899727, 2021).
aspergillosis (1 paper, 2017). Aspergillosis is an infection, growth, or allergic response caused by the Aspergillus fungus. "Interaction of CD28 on T-cell surface with its ligand CD80 (B7-1) or CD86 (B7-2) on APCs and OX40 with OX40L has been shown to contribute to the immunological process of allergic forms of aspergillosis." (PMID 29371571, 2017).
autoimmune hemolytic anemia (1 paper, 2018). Autoimmune hemolytic anemia (AIHA) is an autoimmune disorder in which various types of auto-antibodies are directed against red blood cells causing their survival to be shortened and resulting in hemolytic anemia. "Other miRNAs regulate the expression of co-stimulatory molecules as miR-146b-5p that increases the expression of CD80 potentiating B-T cells synapse in patients with CLL associated with autoimmune hemolytic anemia (AIHA)." (PMID 30322050, 2018).
Ba (1 paper, 2022). "Particularly, we previously published results showing that Ba infection induces DCs maturation, as evidenced by the up-regulation of CD86, CD80, CCR7, CD83, MHC-II, MHC-I and CD40 at 24 h post-infection." (PMID 36441810, 2022).
cerebral malaria (1 paper, 2021). A sequestration of Plasmodium falciparum in the brain, which can cause coma and/or seizures. "In studies of mice with cerebral malaria, EPO treatment significantly inhibited DCs differentiation and reduced expression of costimulatory markers CD80 and CD86, and TLRs." (PMID 33796104, 2021).
cervical disease (1 paper, 2021). "What stood out in the tables was the patients afflicted with the cervical disease showed positive correlation significantly, such as famous immune checkpoint genes (CTLA4, TIGIT, HAVCR2, LAG3, etc.)and costimulatory genes like ICOS, CD80, CD40, and so forth." (PMID 33694292, 2021).
Chagas cardiomyopathy (1 paper, 2022). A disease of the cardiac muscle developed subsequent to the initial protozoan infection by trypanosoma cruzi. "For the first time, our data highlight the role of CD80 in modulation of Treg lymphocytes activation in patients with CARD, highlighting a key molecule in the development of Chagas cardiomyopathy." (PMID 35665256, 2022). "Here, we highlighted for the first time the role of CD80 in modulation of Treg lymphocyte activation in CARD patients, maybe by performance with CD28 receptor, pointing out a key molecule in the development of Chagas cardiomyopathy." (PMID 35665256, 2022).
Chlamydial infection (1 paper, 2008). "This suggests that significantly high expression of CD80 may lead to increased activation of TH1 cells during Chlamydial infection." (PMID 18828896, 2008).
cholestasis (1 paper, 2021). Impairment of the bile flow caused by obstruction within the liver, or outside the liver in the bile duct system. "We conclude that short-term cholestasis leads to a pro-inflammatory reaction mediated by CD80+ cells, while chronic tissue damage is associated with a shift to an increasing number of MDMs with a dominant anti-inflammatory CD163+ cell fraction." (PMID 33918803, 2021).
cholesteatoma (1 paper, 2022). A pathologic process characterized by the proliferation of keratinizing squamous epithelium resulting in the accumulation of keratin and cells in the middle ear and/or mastoid. "In the group analysis, the cholesteatomas with advanced ossicular erosion contained a higher number of cells expressing the M1 marker CD80 as well as a higher M1/M2 ratio than the less erosive cholesteatomas (Wilcoxon test, p < 0.05)." (PMID 36013064, 2022). "The findings revealed that cholesteatomas with more extensive ossicular erosion demonstrated a significantly higher number of M1 (CD80+) cells and a higher M1/M2 ratio than less invasive cholesteatomas (Wilcoxon test, p < 0.05)." (PMID 36013064, 2022). "In the present study, human cholesteatoma specimens acquired during tympanomastoidectomy were retrospectively retrieved and immunohistochemically characterized using a combination of antibodies labeling M1 macrophages (CD80), M2 macrophages (CD163), and total macrophages (CD68)." (PMID 36013064, 2022).
chronic hepatitis (1 paper, 2024). An active inflammatory process affecting the liver for more than six months. "We isolated hepatic macrophages from CCl4-induced chronic hepatitis mice and analyzed the expression levels of CD80 (M1 markers) and CD206 (M2 markers)." (PMID 38399475, 2024).
chronic lymphocytic leukemia (1 paper, 2018). "Indeed, an increased expression of both CD86 and CD80 in response to TLR9 stimulation was shown in chronic lymphocytic leukemia, but not in response to TLR7 stimulations." (PMID 29805758, 2018).
cryptococcal infection (1 paper, 2018). "Scavenger receptor A (SRA)−/− mice have an increased accumulation of DCs in the lungs during cryptococcal infection, and these DCs have enhanced surface expression of co-stimulatory molecules CD80 and CD86, which leads to improved fungal clearance." (PMID 29543719, 2018). "Impaired accumulation of lung DCs occurs during cryptococcal infection in MARCO−/− mice, and these DCs have decreased expression of CD206, but increased expression of the costimulatory molecules CD80 and CD86." (PMID 29543719, 2018). "The IL-17−/− mice have reduced expression of MHC II, CD80 and CD86 on DCs at 4–8 weeks post-cryptococcal infection compared to WT mice." (PMID 29543719, 2018).
cryptogenic organizing pneumonia (1 paper, 2018). Cryptogenic organizing pneumonia (COP) is a form of idiopathic interstitial pneumonia characterized pathologically by organizing pneumonia (OP) that presents with non-specific flu-like symptoms, as well as cough and dyspnea and where no etiological agent is found. "In comparison, in bronchiolitis obliterans organizing pneumonia (now known as cryptogenic organizing pneumonia), an idiopathic interstitial lung disease believed to be secondary to epithelial damage, CD80 is upregulated in AECs without concurrent upregulation of CD86 or MHC class II expression." (PMID 30319613, 2018).
cutaneous squamous cell carcinoma (1 paper, 2023). "In contrast, in cutaneous squamous cell carcinoma, CD80 which is highly expressed by tumor cells has been shown to mediate cancer cell proliferation, T-cell suppression, and failure through contact with CTLA4." (PMID 36892747, 2023).
dementia (1 paper, 2020). Loss of intellectual abilities interfering with an individual's social and occupational functions. "The phenotypic transformation from homeostatic microglia towards reactive microglia in dementia pathologies is associated with TREM2, HLA-DRA, ENTPD1 (CD39), CD80 (B7-1), CD86 (B7-2), CCR5, CD274, ITGAX (CD11c), TIMD4 and MRC1." (PMID 33113879, 2020).
depression (1 paper, 2022). "For the elderly with some level of depression, triple-positive cells for CD14+CD80+CD86+ showed a decreasing trend (p = 0.0611)." (PMID 36193083, 2022).
encephalitis (1 paper, 2018). An acute inflammatory process affecting the brain parenchyma. "A few days later (days 12–16), when the mice develop clinical signs of encephalitis, the expression of chemokines in the eye peaks and there is a clear increase in CD45, as well as increased expression of MHC, CD80, CD86, and CD68." (PMID 29802245, 2018).
endometrioid ovarian cancer (1 paper, 2013). "Among 570 endometrioid ovarian cancer cases, minor alleles at an intronic CD80 tagSNP rs13071247 were associated with a 73% increased risk of mortality (p = 8.0×10−4)." (PMID 23382860, 2013).
enthesitis (1 paper, 2025). Inflammation at the site of insertion of ligaments, tendons, and other fibrous structures into bone. "Other key genes involved in enthesitis were up‐regulated including CSF2 (encoding granulocyte–macrophage CSF), IL12B, IL6, and notably CD80 and CD83 encoding the M1‐associated costimulatory receptors." (PMID 40320905, 2025).
gout (1 paper, 2017). A condition characterized by painful swelling of the joints, which is caused by deposition of urate crystals. "We found a significantly lower expression of CD80, one of the markers of M1 macrophages, in gout patients than in RA patients." (PMID 29056937, 2017).
Graves' orbitopathy (1 paper, 2015). "The present study was designed to investigate the expression of mRNA of the immune regulatory molecules FOXP3, CTLA-4/CD28/CD80/CD86, and CD40/CD40L in the orbital tissues from patients who underwent orbital decompression due to Graves' orbitopathy to assess their role in the inflammatory process." (PMID 25653477, 2015).
hematoma (1 paper, 2024). A hematoma is a collection of blood from a vascular structure into an extravascular space. "It is concluded that CD80 has a good prospect in the research of hematoma vaccine." (PMID 39575257, 2024).
hepatitis B (1 paper, 2024). "Studies on CD80 expression in the context of hepatitis B vaccination have not been reported, although similar studies have been conducted for HIV-infected individuals." (PMID 38555445, 2024).
histiocytic neoplasm (1 paper, 2024). Histiocytic tumors are a heterogeneous group of tumors and tumorlike masses commonly associated with histologically identical extracranial lesions. "These two reports suggest that CD80 could also be a marker of histiocytic neoplasms." (PMID 39224452, 2024).
hypersensitivity pneumonitis (1 paper, 2021). Hypersensitivity pneumonitis (HP) is a pulmonary disease with symptoms of dyspnea and cough resulting from the inhalation of an antigen to which the subject has been previously sensitized. "Much like in severe COVID-19, hypersensitivity pneumonitis is characterized by a massive influx of activated T cells in the lungs and a high expression of B7 (i.e. mouse CD80/CD86 molecules) by alveolar macrophages." (PMID 34075090, 2021).
idiopathic membranous nephropathy (1 paper, 2018). "In a total of 55 patients with biopsy-proven MCD and 26 patients with biopsy-proven idiopathic membranous nephropathy, CD80 and cytotoxic T-lymphocyte antigen-4 (CTLA-4) levels in serum, urine and renal tissue were analyzed." (PMID 30083478, 2018).
immunotoxicity (1 paper, 2020). "The lower levels of CD80+ and CD86+ expressions in peripheral blood lymphocytes in our BIAA model were in agreement with a report study which showed that BZ-induced immunotoxicity could be due to lower levels of CD80+ and CD86+." (PMID 32256652, 2020).